CCDC185 (coiled-coil domain containing 185)
Synonyms: C1orf65; FLJ35728
Tractability: PROTAC: UniProt records ubiquitination sites on it; ubiquitination databases record sites on it.
Gene: Protein-coding gene on chromosome 1 (223,393,415 to 223,395,465, forward strand). Ensembl gene ENSG00000178395.
Gene Ontology:
Molecular function: protein binding
Genetic constraint (gnomAD): Loss-of-function variants: 0 observed, 1.09 expected, observed/expected ratio (o/e) 0, 90% interval 0 to 1.7. That is too few expected variants to judge how well the gene tolerates losing a copy. Missense variants: 982 observed, 810.48 expected, observed/expected ratio (o/e) 1.21, 90% interval 1.15 to 1.28. Synonymous variants: 381 observed, 334.49 expected, observed/expected ratio (o/e) 1.14, 90% interval 1.05 to 1.24.
Homologues: Orthologues: chimpanzee CCDC185 (98% identical), macaque CCDC185 (95% identical), rabbit CCDC185 (64% identical), pig CCDC185 (61% identical), mouse Ccdc185 (54% identical), rat Ccdc185 (54% identical).